CCND1 (cyclin D1)
Diseases named in the same sentence as CCND1 in open-access papers (continued):
Sharing a sentence is not in itself a finding about the gene and the disease.
cancer (continued). "For hub PCGs, CCND1 and SMAD4 are cancer driver genes that mediated cell cycle and TGF-β signaling which are all cancer development related biological processes." (PMID 27580177, 2016). "Second, we constructed the pan-cancer FFLs subnetworks that were targeted by the nine anticancer drugs, in which ATO has two drug targets, CCND1 and JUN." (PMID 26655252, 2016). "BMI-1 knockout was shown to upregulate DKK1 and to target cancer cells via subsequent downregulation of MYC and CCND1." (PMID 26935956, 2016). "As expected, hypoxic exposure significantly increased cancer stemness related factors (c-Myc, Klf4, Nanog, and Oct4) and Wnt/β-catenin signaling components (Wnt1, TCF4, and Cyclin D1)." (PMID 26965643, 2016). "Among them, several genes were related in cancer pathway such as EGFR, RARA, FGF2, FGFR1, FGFR2, FGFR3, KIT, and CCND1." (PMID 27016420, 2016). "Overexpression of CCND1 is tumorigenic, as supported by evidence that MMTV-driven CCND1 overexpression is sufficient for mammary hyperplasia and carcinoma development in transgenic mice." (PMID 26799586, 2016). "Studies on the TC21 regulation pathway mostly focused on its role in cancer, which mediates its effects via the PI3K-Akt pathway, NF-κB, and cyclin D1 that are all related with cerebral ischemia reperfusion injury." (PMID 25884595, 2015). "In conclusion, cyclin D1 induces DICER1 and thereby promotes the maturation of let-7 miRNA, and then drive cancer progression in part via miRNA biogenesis." (PMID 25702703, 2015). "Other large CNA genes gained or lost in the correct direction to drive cancer are PIK3R1 and CASP3 in BACA, and NRAS and CCND1 in CLAC." (PMID 26560147, 2015). "In present study, we generated a OS metastasis related miRNA profiling and found one of the top ranked miRNAs miR-195 inhibit the cancer metastasis in vivo and in vitro partly through targeting the cell cycle gene-CCND1(CyclinD1)." (PMID 25823925, 2015). "Our results also showed that cyclin D1 is required for Nutlin-3 and TAX-induced let-7 expression in cancer repression and the cell death response." (PMID 25702703, 2015). "We also confirmed the positive correlation between cyclin D1 and DICER1 in cancer cells acquired from N3-treated MCF-7 mammospheres." (PMID 25702703, 2015). "We have shown recently that the La protein is overexpressed in solid tumors, supports proliferation and mobility of cancer cells and established that La promotes IRES-mediated translation of cyclin D1 (CCND1) in HeLa cells." (PMID 25520193, 2015). "The mRNA level of proliferation-related gene ki-67 and G1/S transition related genes, CCND1 and TAF10 was evaluated to confirm the effect of Dppa4 knockdown on cancer cell proliferation." (PMID 26063247, 2015). "Some of them, such as UBE2C, CASP3, CCND1/2, STAT3, JAK2 and MMP-9, have been used as markers of cancer malignancy." (PMID 26603105, 2015). "Compared with the normal tissues, the acrophases of Per2 and CDK1 were earlier in precancerous lesions, and the acrophases of Cyclin D1, CDK1 and Cyclin B1 occurred later in the cancer cells." (PMID 25950458, 2015). "The ability of IL-24wt to markedly inhibit β-catenin and cyclin D1 expression and activate GSK-3, determined by its phosphorylation, makes IL-24-based cancer therapy attractive." (PMID 26009991, 2015). "Among 60 genes selected for targeted sequencing, amplifications of the CCND1 and ERBB2 genes were detected in both ctDNA and the primary cancer in this patient." (PMID 26669280, 2015). "Similar to other cancers, recurrent amplification of 7p11.2, 8q24.21, and 11q13.2, harboring EGFR, MYC, and CCND1, has previously been reported in ESCC." (PMID 26465158, 2015).
cancer (continued). "In Patient ID-18, amplifications of the CCND1 and ERBB2 genes were suspected in ctDNA and the genes were also clearly amplified in the primary cancer by aCGH analysis." (PMID 26669280, 2015). "The CDK4-cyclin D1-p16 retinoblastoma protein (RB1) pathway (CDK4 pathway) promotes the G1-S cell cycle transition and is commonly dysregulated in most cancers." (PMID 26252490, 2015). "Previous studies showed that miR-34a targets the oncogenes CDK4, CDK6, CCND1, MET, and BCL2, whereas miR-497 targets the oncogenes CCND2 and BCL2 in various types of cancer." (PMID 25909221, 2015). "USP2 stabilizes cyclin D1 in order to maintain human cancer cell growth; targeting USP2 is therefore an effective approach to induce growth suppression of cancer cells addicted to cyclin D1 expression." (PMID 26097878, 2015). "Our results showed that vernodalin regulates cancer cell apoptosis through activation of FOXO transcription factors and its downstream targets (Bim, p27Kip1, p21Waf1/cip1, cyclin D1, cyclin E) as examined by Western blots." (PMID 26643256, 2015). "Some target genes are involved in oncogenesis, such as c-MYC and cyclin D1 regulating cancer proliferation, MMP-7 regulating cancer invasion." (PMID 25658088, 2015). "Cyclin D1 (CD1) is the most prominent G1-phase Cyclin and has been reported as an oncogenic driver in cancer cells." (PMID 25192188, 2014). "Our results demonstrated that ISO is a promising chemopreventive agent via upregulating mkp-1 mRNA stability, which is distinct from its cancer therapeutic effect with downregulation of XIAP and cyclin D1 expression." (PMID 24797581, 2014). "In SAS cells, overexpression of NM23-H1 slightly downregulated cyclin D1 and B1 whereas knockdown of NM23-H1 upregulated them, consistent with published reports in other types of cancer cells." (PMID 25277180, 2014). "Molecules such as Her2, EGFR, VEGFR, ALK, AKT, p52, cyclin D1, Met, Cdk4, HIF-1α or MMP2 which play important roles as oncogenes and are involved in essential pathways of cancer are described to be client proteins of HSP90." (PMID 24978439, 2014). "Very few regions of high-level copy number gain were found, an exception being amplification around the CCND1 oncogene on chr11q13.3 and at the FGFR3 locus on chr4p16.3, each in a single cancer (#4121 and #615, respectively)." (PMID 24777035, 2014). "Furthermore, cyclin D1 may be an important prognostic indicator for human cancer." (PMID 24602161, 2014). "dFMGEN, a novel genistein derivative, is a candidate for cancer therapy, arresting the cell cycle at G1 phase with significant reduction of CDK4 and CCND1 protein levels." (PMID 24605326, 2014). "The Hep55.1C tumors being vascularized, expressing some human cancer and HCC markers like osteopontin, cyclin D1 and AFP, the model seemed suitable to analyze the effect of anti-cancer or anti-fibrotic drugs." (PMID 25203629, 2014). "The TCF/LEF downstream molecules c-myc, cyclin D1 and MMP7 were also increased significantly in cancer cells." (PMID 23737966, 2013). "An unchecked or hyperactivated Cyclin D1/CDK4 complex often leads to uncontrolled cell division and therefore cancers." (PMID 23800091, 2013). "Levels of staining of Cyclin D1 and Bcl-2 in TSCC cancer tissues were inversely correlated with miR-195 levels." (PMID 23451060, 2013).
cancer (continued). "As one of the crucial cancer pathways, the RTK/ERK pathway is said to be one of the important links in cancer's development, containing a number of genes (EGFR, EGF, CCND1, MAPK3, etc.)." (PMID 24223781, 2013). "Most of these regions have been validated to encompass or closely near to cancer related genes such as MDM2, MYC, EGFR, ERBB2, CCND1, ARNT." (PMID 23285074, 2012). "SMAD3 also contributes to the 3-indole-induced G1 arrest in cancer cells and its inhibition depends on CCND1-CDK4 (cyclin-dependent kinase 4) action in breast cancer cells overexpressing CCND1, which appeared upregulated by A1789T." (PMID 22646717, 2012). "We next investigated various gene products involved in cancer progression (COX-2), proliferation (cyclin D1) and apoptosis (caspase-3) by immunohistochemistry in the DLP of Group 3 TRAMP mice." (PMID 22427843, 2012). "The rigidity-dependent cancer cell lines A549 and MDA-MB-231 sustain the expression of cyclin D1 when cultured in serum on polyacrylamide gels that have mechanical properties similar to that of soft tissue such as lung or breast." (PMID 22623999, 2012). "The present study was designed to investigate the effects of cyclooxygenase (COX) inhibitors in combination with taxol on the expression of cyclin D1 and Ki-67 in human ovarian SKOV-3 carcinoma cells xenograft-bearing mice." (PMID 22949827, 2012). "Using tissue microarrays and immunohistochemistry, the fraction and intensity of cyclin D1 expression was evaluated in 527 incident CRC cases from the Malmö Diet and Cancer Study." (PMID 21888663, 2011). "In HPV+ cancers, p16 was expressed at high levels and cyclin D1 at low levels, with the converse in HPV- cancers." (PMID 21447181, 2011). "Concerning cell cycle markers, all cancer cells tested treated with IC50 during 24 h and 48 h showed a noticeable decrease in cyclin D1 expression." (PMID 21935420, 2011). "Accumulating evidence has shown that hypermethylation in the promoter region of CDKN2A or overexpression of CCND1, which results in RB1 dysfunction, frequently occurs in various types of cancers." (PMID 21447152, 2011). "To this end, we analyzed by immunofluorescence and quantified the level of expression of two β-catenin/TCF target genes (Ccnd1/Cyclin D1 and Lef1) in colon ACF and carcinomas of Apcmin/+Vdr+/+, Apcmin/+Vdr+/- and Apcmin/+Vdr-/- mice." (PMID 21858154, 2011). "However, in certain cancers where ERβ is considered protective, antiproliferative effects are achieved by cell cycle growth arrest for example by down-regulation of the cyclin D1 (CCND1) gene thereby preventing cellular progression from the G1 to S-phase of the cell cycle." (PMID 20146809, 2010). "C-myc, cyclin A, cyclin B1, cyclin D1, CDK2, and survivin contributed to the separation between the cancer and non cancer groups." (PMID 20504322, 2010). "Five markers increased in cancer patients by 39–246%: carbonyls, lactate dehydrogenase, metalloproteinase-9 (MMP-9), Ki67 and Cyclin D1 (CycD1) (P⩽0.01)." (PMID 19789535, 2009). "Moreover, the CCND1 A870G genotype or the presence of the variant truncated CCND1 transcript (preferentially encoded by the A870G genotype) was associated with a younger age of cancer onset in subjects with hereditary nonpolyposis colorectal cancer (HNPCC)." (PMID 16495921, 2006). "The CCND1 A870G polymorphism appeared to confer an elevated risk for cancers in the distal colon or rectum (rectum to splenic flexure) (OR, 2.84; 95% CI, 1.27–6.33), but not for proximal cancers (splenic flexure to caecum) (OR, 1.26; 95% CI, 0.61–2.60) in the women." (PMID 16495921, 2006).
cancer (continued). "Moreover, the levels of downstream molecules (including p-eIF4E, cyclin D1, snail, and Bcl2) regulated by RACK1 were also decreased after SENP3 knockdown, which is consistent with the impact of SENP3 on cancer hallmarks." (PMID 39755756, 2025). "In addition to ecDNA, we also found evidence of CCND1 upregulation through putative enhancer hijacking resulting from chromothripsis-mediated rearrangement of regulatory elements, highlighting the diversity of mechanisms by which chromothripsis may contribute to cancer development." (PMID 39185963, 2025). "CCND1 is one of the most amplified genes in human cancers, but its effects on RS and DNA damage repair have not been extensively characterized." (PMID 40608419, 2025). "However, in cancer cells, hyperphosphorylated STAT3 activates oncogenic transcription factors such c-Myc, Cyclin-D1, Bcl-xL, VEGF, and Oct-4, leading to enhanced cell proliferation and survival, as well as aggressive cancer cell stemness." (PMID 40075607, 2025). "Altogether, these findings demonstrate that DHC has cytostatic properties against cancer cells, especially in the presence of TNF-α, by inducing cell cycle arrest in the G1 phase correlated with the downregulation of cyclin D1 expression and RB protein phosphorylation." (PMID 40507823, 2025). "The study population included 690 ER+ patients that had outcome data available, did not have distant metastases at the time of surgery, and had Cyclin D1 CSI expression levels for at least 100 cancer cells in the TMA core IF-IHC image." (PMID 40099197, 2025). "MYC, a well-known eccDNA-amplified driver gene which promotes cancer cell proliferation, immortalization and cross-resistance, was identified in the most cancer types (11 of 12) with the highest EGIS, followed by CCND1 (11 of 12), H3-5 (10 of 12), YWHAZ (10 of 12) and GAPDHS (10 of 12)." (PMID 40478912, 2025). "In cancer progression, STAT3 mainly promotes oncogenic transcription through well‐established phosphorylation‐dependent pathways, such as the JAK/STAT3 or IL‐6/STAT3 axes, which upregulate cyclin D1, Bcl‐xL and survivin." (PMID 40464702, 2025). "Moreover, several genes, including PTK2, CCND1, and ERBB2, were identified as being closely related to the occurrence and progression of cancer, with their expression levels significantly correlating with patient prognosis." (PMID 40567661, 2025). "Hence, it is possible that the anti-cancer properties of PC were aided by a decrease in the active form AKT1 and ERK1/2 and the downregulation of Cyclin D1, Cyclin E, and EMT pathway genes." (PMID 40319292, 2025). "In this context, LACT, through its iron-sequestering activity, and MES, through inhibition of β-catenin signaling and downstream effectors such as CCND1 and MYC, may act synergistically to disrupt cancer-specific vulnerabilities." (PMID 40699726, 2025). "Several studies have previously investigated the roles of CCND1, GABPA, HIF1A, and SOX6 in various diseases, including cancer and cardiovascular diseases, but the specific roles of these genes in HF and their interaction within the context of the PI3K/AKT pathway have not been well-explored." (PMID 40818967, 2025). "Silencing METTL7B leads to downregulation of the cell cycle regulator cyclin D1 (CCND1) and upregulation of cyclin-dependent kinase 4 inhibitor (CDKN4), resulting in G0/G1 phase arrest in cancer cells and a significant reduction in their proliferative capacity both in vitro and in vivo." (PMID 41194259, 2025). "Although this CDK4/6-Rb pathway is frequently altered in cancers, it is not strictly essential for cell division, as deletion of Ccnd1, Cdk4, or Cdk6 is not embryonically lethal in mice." (PMID 41226361, 2025).
cancer (continued). "Kaiso regulates Wnt/β-catenin target genes, including Wnt11, Cyclin D1, and Matrilysin 7, in various cancers (33, –, 35), but these were absent in classical VN and VP-MCC cell lines, while variant MCC cells expressed only Cyclin D1 (data not shown)." (PMID 40407323, 2025). "Furthermore, the presence of the pathogen inhibited the expression of cyclin D1 and CDK4 in cancer cells, and increased CDK inhibitor p21CIP1/WAF1 level compared to uninfected control cells." (PMID 41228271, 2025). "Although previous studies in mice have indicated that concurrent deficiencies in POLΘ and ATM can be partially synthetic lethal, our data suggest that cyclin D1 overexpression may be a useful biomarker for combined POLΘ and ATM inhibition in cancer treatment." (PMID 40608419, 2025). "In various cancer cell lines, CARTPT acts as an oncogene, promoting cellular survival through the activation of the ERK pathway, stimulation of pro-survival molecules, inhibition of apoptosis, and an increase in cyclin D1 levels." (PMID 40870889, 2025). "The results indicate that varying solanine concentrations (10, 20, and 30 μM) considerably reduce the expression of iNOS, IL-6, cyclin-D1, and PCNA proteins in KB-ChR-8-5 cells, suggesting that solanine has the ability to significantly decrease the formation of malignant tumors." (PMID 39124760, 2024). "Our analysis led to the identification of PIK3R1, CCND1, TERF2IP, SLC25A4, CAPN2, and TXN as hub genes, which could potentially serve as targets for interventions in both MN and cancer." (PMID 38846934, 2024). "This study also sheds light on the downregulation of factors related to metastasis and angiogenesis, such as Cyclin D1, VEGF, and MMP-9, under combined treatment, emphasizing the potential therapeutic promise of this strategy for controlling cancer cell proliferation and metastasis." (PMID 38790669, 2024). "In the context of cancer, the insertion of super-enhancer elements from different chromosomes into the intergenic region flanked by the MYEOV-3′-putative enhancer and CCND1 culminates in the emergence of an expansive active regulatory domain spanning the CCND1 gene locus." (PMID 39139450, 2024). "Collectively, these findings underscore the essential partnership between MAT1A and CCND1 in orchestrating NSCLC glycolysis and tumorigenesis, providing novel insights into the molecular mechanisms underpinning this metabolic reprogramming in cancer." (PMID 39438468, 2024). "Inhibiting the cyclin D1 and CDK4/6 complex can induce G1 phase arrest in cancer cells." (PMID 38338430, 2024). "CCND1 (Cyclin D1), MPP2 (Membrane palmitoylated protein 2), Bax, Bcl2, HIF1A and VEGFA are transcriptionally regulated molecules that are related to cell proliferation, apoptosis and cancer cell invasion and metastasis processes." (PMID 39834948, 2024). "CDK1, CCND1, and PCNA play distinct roles in different phases of cell cycle and have been identified as pivotal genes in the development and progression of different cancer types, including colon, liver, and gynecological tumors." (PMID 38831458, 2024). "Additionally, LINC01405 upregulation led to the increased cell populations, proliferation, and upregulation of critical cancer‐related genes, including AKT1, AKT3, mTOR, WNT3A, SMAD3, CYCLIN D1, CYCLIN D2, BCL2, and GSK3B." (PMID 38225865, 2024). "Oncogenes that are well-known to be amplified in cancer include MYC, EGFR, ERBB2, CCND1, and MDM2." (PMID 38611020, 2024). "Cyclin D1 (CCND1) is upregulated in many solid cancers, promoting cancer progression." (PMID 38225605, 2024). "Furthermore, survivin, Bcl-2, cyclin D1, and VEGF were also found to be transcriptionally activated leading to enhanced cell survival, angiogenesis, and cancer progression." (PMID 38719798, 2024).